MYC (MYC proto-oncogene, bHLH transcription factor)
Diseases named in the same sentence as MYC in open-access papers (continued):
Sharing a sentence is not in itself a finding about the gene and the disease.
pancreatic cancer (continued). "One of the most critical molecular players involved in diverse cellular signaling pathways in many cancers including pancreatic cancer is the MYC proto-oncogene." (PMID 33168807, 2020). "We found that TPL, cytotoxic to both pancreatic tumor cells and CAFs, disrupted SEs in a manner that resulted in the downregulation of SE-associated genes (e.g., BRD4, MYC, RNA Pol II, and Collagen 1) in both cell types at mRNA and protein levels." (PMID 33168807, 2020). "Our findings suggest that G2M score was elevated in cell proliferation gene sets such as E2F targets, MYC targets v1 and v2, and mitotic spindle formation in two large pancreatic cancer cohorts." (PMID 33036243, 2020). "Some studies have shown elevated expression of c-MYC oncogene or its protein product c-Myc in pancreatic cancer." (PMID 32362830, 2020). "Specifically, the activation of MYC triggers rapid recruitment of mast cells to the tumour site to promote tumour expansion in pancreatic cancer." (PMID 32175651, 2020). "One previous study has demonstrated the important roles of mast cells in MYC activation and the potential tumour expansion promoted by mast cells in pancreatic cancer." (PMID 32175651, 2020). "Recent studies enumerated that c-MYC represents a central oncogene in pancreatic cancer and its expression correlated with the perineural invasion and poor prognostic features." (PMID 32604971, 2020). "We conducted gene-environment analyses with four SNPs (NR5A2 rs2816938, MYC rs10094872, PDX1 rs9581943 and a chromosome 13q22 SNP, rs4885093) significantly associated with pancreatic cancer risk." (PMID 32456644, 2020). "For instance, NFATc1 induced malignant growth phenotype in pancreatic cancer cells by upregulating MYC and promoted metastasis of mammalian cancer cells via MMP-2 upregulation." (PMID 31040921, 2019). "BPTF knockdown suppressed the proliferation of pancreatic cancer cells and delayed the development of c-MYC-driven pancreatic tumors." (PMID 31769422, 2019). "JQ1, one of the most studied selective inhibitors of BET proteins, has been shown the inhibition of pancreatic cancer growth in vitro and in vivo through repression of c-MYC, FOSL and HMGA2." (PMID 30201002, 2018). "Since c-MYC has been shown in the context of pancreatic cancer cells to drive SLC7A5 transcription, in our mouse model we have tested the relative role of the RAF-MEK-ERK and Pi3’K pathways for Slc7a5 transcription." (PMID 30241549, 2018). "For example, in a MYC mouse model of pancreatic cancer, sustained activation of c-Myc in β cells triggers increases the expression of the inflammatory cytokine interleukin-1β (IL-1β)." (PMID 28333115, 2017). "Suppression of MYC via Omomyc further induced changes in the microenvironment of pancreatic tumor cells." (PMID 28333115, 2017). "As it relates to pancreatic cancer, the disease focus of the current study, c‐MYC was found to be originally amplified in more than 30% of PDAC by using interphase fluorescence in situ hybridization, as well as overexpressed in more than 40% of tumors." (PMID 28275007, 2017). "The nuclear factors of activated T cells (NFAT) family of transcription factors has been found to be overexpressed in pancreatic tumors and is responsible for increased c-MYC gene expression." (PMID 28383487, 2017). "BET inhibitors attenuate cell growth and survival in several hematologic cancer models, but also in pancreatic cancer models, at least in part through the down-regulation of the critical oncogene MYC." (PMID 28423491, 2017). "The analysis of this model suggested also that mitogen-activated kinase and c-MYC stabilization are the main driving forces for the development of an aggressive metastatic pancreatic cancer." (PMID 29156578, 2017). "These SNPs represent independent risk variants at previously identified pancreatic cancer risk loci on chr1q32.1 (NR5A2), chr8q24.21 (MYC) and chr5p15.33 (CLPTM1L-TERT) as per analyses conditioned on previously reported susceptibility variants." (PMID 27579533, 2016).
pancreatic cancer (continued). "The probes in the panel (1q21, 7p12, 8q24, and 9p21) were first evaluated on 30 selected samples of tumor tissue (CCA and pancreatic cancer) where gain of 8q24 (MYC) was observed in 44% of the tumor cells analyzed." (PMID 27127503, 2016). "In summary, these data indicate that BPTF is necessary for the initiation and maintenance of c-MYC-driven pancreatic tumours." (PMID 26729287, 2016). "The MYC proto-oncogene is overexpressed in many types of cancer, including pancreatic cancer where it has been shown to decrease sensitivity to gemcitabine." (PMID 27517489, 2016). "c-MYC signatures correlated with c-MYC expression levels in BL, colorectal, prostate and pancreatic carcinomas." (PMID 26729287, 2016). "Overall, our result demonstrates that MUC16 mediated c-MYC expression regulates physiology and biosynthetic processes of pancreatic cancer cells." (PMID 26046375, 2015). "Proto-oncogene c-MYC is considered as a master regulator of cellular metabolism, growth and proliferation and is deregulated in multiple solid tumors, including pancreatic cancer." (PMID 26510913, 2015). "In order to understand the molecular basis of silibinin-mediated c-MYC expression regulation and metabolic reprogramming of pancreatic cancer cells, we investigated the effect of silibinin treatment on STAT3 activation, which enhances c-MYC expression." (PMID 26510913, 2015). "Ectopic expression of c-MYC in MUC16 knockdown pancreatic cancer cells restores the altered cellular physiology." (PMID 26046375, 2015). "It induces metabolic reprogramming in pancreatic cancer cells by reducing expression of a key metabolic regulator, c-MYC, through reduced activation of STAT3." (PMID 26510913, 2015). "We observed a positive correlation between MUC16 and c-MYC expression in human pancreatic tumor specimens." (PMID 26046375, 2015). "We found that BET inhibitors decrease growth of pancreatic cancer cells through repression of both c-MYC and FOSL113." (PMID 25807524, 2015). "For diffuse large B-cell lymphomas (DLBCL) and pancreatic cancer cells an NFATc1-directed up-regulation of the MYC gene has been described which appears to be due to the recruitment of histone acetylases to the MYC promoter." (PMID 22764736, 2012). "Notably, β-catenin-c-MYC signaling pathway is crucial in pancreatic cancer metabolism, especially in the regulation of glucose metabolism 38-40." (PMID 40083702, 2025). "Since the MYC mRNA is known to be bound and stabilized by IGF2BP1 in a m6A-dependent manner, the authors speculated that gemcitabine might interfere with the WTAP/MYC/IGF2BP1 axis to inhibit pancreatic cancer progression." (PMID 40427100, 2025). "Moreover, our RNA-seq data obtained from the pancreatic cancer cell line Mia-Paca2 revealed a substantial reduction in ASS1 mRNA levels following MYC knockdown." (PMID 40732268, 2025). "The LLPS inhibitor 1,6‐hexanediol can downregulate MYC transcription levels and inhibit pancreatic cancer growth, which may be related to the disruption of the MYC super enhancer's function." (PMID 40211955, 2025). "We have demonstrated the generalizability of the MYC-mRNA drug’s therapeutic efficacy across different pancreatic cancer models of PSN1, MIA-Paca-2, and PANC1 and validated its inhibition of the high c-MYC-expressing PSN1 in vivo with significant survival outcome." (PMID 40949131, 2025). "To prove that the c-MYC-mRNA drug inhibited c-MYC in vivo in a titratable dose-dependent manner in lethal pancreatic cancer, we titrated the dose of the MYC-mRNA drug from the first in vivo experiment of 3× IC50 (3.6 μg) to 6× IC50 (21.6 μg) and 9× IC50 (32 μg)." (PMID 40949131, 2025). "The KRAS/ERK/c-MYC axis is a major driver of pancreatic cancer tumorigenesis." (PMID 40100307, 2025). "Previous studies have examined the role of MYC in the pancreatic cancer super-enhancer network." (PMID 40216980, 2025). "A higher amount of MYC eRNA is observed in chronic pancreatitis and in pancreatic cancer patients." (PMID 40216980, 2025).
pancreatic cancer (continued). "Downregulating MYC transcription levels inhibits pancreatic cancer growth." (PMID 40211955, 2025). "Further mechanistic investigations revealed that tiRNA-Val-CAC-2 could interact with RNA-binding protein FUBP1, leading to the increase of FUBP1 protein stability, which further promotes pancreatic cancer metastasis by c-MYC transcription." (PMID 38443680, 2024). "Since tiRNA-Val-CAC-2 is capable of promoting FUBP1-mediated c-MYC transcription in pancreatic cancer cells, we further hypothesized that tiRNA-Val-CAC-2 may promote metastasis in pancreatic cancer through FUBP1 to active c-MYC transcription." (PMID 38443680, 2024). "Of note, rescue experiments confirmed that tiRNA-Val-CAC-2 could influence pancreatic cancer metastasis via FUBP1-mediated c-MYC transcription." (PMID 38443680, 2024). "Taken together, these results suggest that FUBP1 may play a critical role in the regulation on c-MYC transcription in pancreatic cancer probably through interaction with FUSE motif." (PMID 38443680, 2024). "We wondered whether the dependence of pancreatic tumours on the RUVBL1/2 complex is conveyed by high MYC expression, so we did a series of experiments using the RUVBL1/2 inhibitor CB-6644 to address this question." (PMID 38821858, 2024). "We then analysed whether MYC expression is responsible for the sensitivity of pancreatic cancer cells to RUVBL1 inhibition." (PMID 38821858, 2024). "Similarly, in pancreatic cancer, hypoxia-induced exosomal circPDK1, which regulates miR-628-3p, promotes glycolysis via MYC activation." (PMID 39769441, 2024). "We next investigated whether ZDHHC20 promotes pancreatic cancer progression by affecting the biological function of MYC." (PMID 38821916, 2024). "Moreover, the observed arrest in S-phase on depletion or inhibition of RUVBL1 was comparable to what was described on silencing MYC in pancreatic cancer cells." (PMID 38821858, 2024). "However, our data with the CHLA-15 line, together with reports such as the sensitivity of c-MYC over-expressing pancreatic cancers to PRMT5 inhibition suggest that threshold and context-dependent effects are important in c-MYC-driven cancers." (PMID 39313128, 2024). "In addition, FAM83H expression was transcriptionally controlled by MYC in liver cancer cells, and FAM83H overexpression was significantly associated with KRAS mutation and EMT gene signature in pancreatic cancer." (PMID 37761326, 2023). "Previous studies have found that the oncogene MYC drives stemness in breast and pancreatic cancer." (PMID 38098005, 2023). "More research into how juglone controls MYC could help explain how therapy works and how pancreatic cancer cells might become resistant to drugs." (PMID 38139993, 2023). "Indeed, inhibition of IGF1/AKT signalling alongside c-MYC or KRAS inhibition increased pancreatic cancer cell clearance and delayed tumour recurrence in these mice." (PMID 37608096, 2023). "Additionally, a recent study found that βIII‐tubulin suppression decreased MYC levels, which in turn sensitised pancreatic cancer cells to ERK inhibition." (PMID 35946957, 2023). "Mast cells assume pivotal roles in MYC activation and may promote tumor growth in pancreatic cancer." (PMID 37256127, 2023). "Additionally, JQ1 effectively inhibited tumor growth in primary pancreatic cancer xenografts in MYC high groups, providing a stratification strategy for MYC-dependent tumors." (PMID 37659057, 2023). "Together, these results suggest that targeting transcription via dual inhibition of TOP1 and BRD4 can specifically target KRAS- and MYC-driven pancreatic tumors and provide viable and clinically applicable therapy for hard-to-treat cancer entities such as PDAC and panNEC." (PMID 37831776, 2023). "In addition to activation of MYC and mTORC signaling, we revealed that pancreatic cancers with HIF-1 high scores were more immunosuppressive by further investigation into the hypoxia-immune profiles." (PMID 34925373, 2021).
pancreatic cancer (continued). "Moreover, the ability of bufalin (a derivative of digoxin) to reduce c-MYC levels was demonstrated in xenograft models of pancreatic cancer." (PMID 32759815, 2020). "In mice with oncogenic Kras, a heterogenic knockout of MYC reduces the development of pancreatic cancer, and physiological elevation of MYC, induced by the insertion of two copies of ROSA-driven MYC, significantly worsened the survival in a mouse model of pancreatic cancer." (PMID 32609742, 2020). "From this point of view, STAT3 and its effector MYC may be a pancreatic cancer driver in hyperglycemia." (PMID 32609742, 2020). "In general, commonly mutated genes in pancreatic cancers did not substantially differ across tumour sites, with the exception of MYC, which was more frequent in the liver." (PMID 31292535, 2019). "In addition to the HDAC1/HDAC2-dependent transcriptional regulation of MYC in pancreatic carcinoma cells, our data collected with RGFP966 suggest that HDAC3 supports the expression of MYC in leukemic cells." (PMID 31561534, 2019). "In contrast, the MYC‐low subgroup is characterized by biological processes that reflect a more differentiated state of pancreatic tumors such as digestion (Normalized Enrichment Score = −2.23 and FDR = 0.00) and glycoprotein metabolism (Normalized Enrichment Score = −1.76 and FDR = 0.00)." (PMID 28275007, 2017). "On the other hand, enhanced c-MYC protein stability by NAD-dependent deacetylase sirtuin-2 (SIRT2) or inhibitor of nuclear factor kappa B kinase subunit epsilon (IKKε) has been demonstrated to increase pancreatic cancer tumorigenicity." (PMID 28383487, 2017). "Interestingly, TCGA analysis revealed up to 90.28% of the pancreatic cancer samples with FAM83A gene amplification also had c-MYC gene amplification." (PMID 28287611, 2017). "The effective role of CCND1 and MYC in 31 pancreatic cancer cell lines are assessed and emphasized." (PMID 29511477, 2017). "The SNP at 8q24.21 is located ~28 kb upstream of MYC, in a susceptibility locus previously reported for bladder cancer (tagged by rs9642880; r2 = 0.64 in 1000G EUR) and ~850 kb upstream of a previously reported pancreatic cancer susceptibility locus." (PMID 27579533, 2016). "On the basis of these findings, we analysed whether the in vivo oncogenic effects of c-MYC are dependent on BTPF using the Ela-Myc model of pancreatic cancer." (PMID 26729287, 2016). "Therefore, ABC294640 causes dose-dependent suppression of two key genes, MYC and RMM2, that drive pancreatic cancer growth and resistance to chemotherapy." (PMID 27517489, 2016). "To determine the causal relationship between STAT3 activation and c-MYC expression in human pancreatic cancer, we investigated the TCGA pancreatic cancer dataset for a correlation between pSTAT3 levels and c-MYC protein expression in 106 primary tumor specimens." (PMID 26510913, 2015). "Furthermore, silibinin treatment reduces STAT3 activation, c-MYC and GLUT1 expression, and the number of proliferating cells in pancreatic tumors, while preventing tumor-induced body-weight loss." (PMID 26510913, 2015). "In pancreatic tumor xenografts treated with NPsiDCLK1, we observed a significant upregulation of let-7a and subsequent downregulation of its downstream target c-MYC (mRNA and protein)." (PMID 24040120, 2013). "This idea is supported by evidence from MYC-driven models where inhibition of glycolysis with LDHA inhibitors or inhibitors of the NAD+ salvage enzyme nicotinamide phosphoribosyl-transferase (NAMPT) led to selective toxicity in MYC-overexpressing pancreatic cancer and glioblastoma cells." (PMID 40126351, 2025). "Likewise, in lung and pancreatic cancers, MYC and MYCN genes are frequently amplified." (PMID 36969025, 2023). "Interestingly, it was illustrated in another research that OLR1 upregulation could enhance c-MYC expression to accelerate pancreatic cancer metastasis." (PMID 34921134, 2021).
pancreatic cancer (continued). "We characterized the function of eukaryotic translation initiation factors (eIFs) in epithelial-mesenchymal-transition (EMT) and metastasis in pancreatic cancer cells to investigate whether eIFs and downstream c-MYC affect EMT and metastasis by joint interference." (PMID 34906136, 2021). "Moreover, the biological contribution of c-MYC to this aggressive form of pancreatic cancer was confirmed by the analysis of adenosquamous characteristics of pancreatic tumors that arose in a c-MYC-induced genetically engineered mouse model of PDAC that our team generated." (PMID 34491463, 2021). "Because U1 Adaptor is a new generation gene silencing technology that may serve as a new therapeutic modality for targeting any oncogene, U1 Adaptors were translated to target KRAS and MYC, and the adaptors strongly inhibit pancreatic cancer cell proliferation." (PMID 31346334, 2019). "Also, MYC pathway appeared as an essential pathway for the survival of Panc1 cells in our study and might serve as a target for treatment of pancreatic cancer." (PMID 31844142, 2019). "Furthermore, deregulation of c-MYC expression has been shown in pancreatic cancer." (PMID 26046375, 2015). "Hence, we conclude that the growth of pancreatic cancer cells in vitro can be suspended (although not completely abrogated) through loss of cell attachment or combined MAPK/ERK/MYC inhibition." (PMID 26158412, 2015). "During the early stages of pancreatic cancer, activation of NOTCH2 signaling led to abnormal MYC upregulation, which drove proliferation and malignant transformation of precancerous lesions." (PMID 41200204, 2025). "tiRNA-Val-CAC-2 is significantly upregulated in metastatic pancreatic cancer lesions, promoting metastasis by enhancing FUBP1 stability and upregulating c-MYC transcription." (PMID 40153423, 2025). "Further, we design a biologically active YTHDF3-derived peptide to competitively inhibit YTHDF3 palmitoylation mediated by ZDHHC20, which in turn downregulates MYC expression and inhibits the progression of KRAS mutant pancreatic cancer." (PMID 38821916, 2024). "As for our study, pathway analysis found known PDAC driver pathways, such as KRAS, MYC, MAPK and WNT signaling pathways, enriched in the five subtypes, which supported their tumor origin." (PMID 38827297, 2024). "The PPRHs tested in combinations targeting both MYC and KRAS were G4-C or I1-T for MYC and PPRH2 or PR for KRAS, in both PC-3 and the previously examined AsPc-1 pancreatic cancer cell lines at a dose of 25 nM per PPRH." (PMID 39457457, 2024). "In pancreatic cancer, members of the SUMO pathway including SAE2/UBA2, SAE1, or UBE2I, have been found to synthesize lethal MYC interaction." (PMID 35965507, 2022). "BMI1, ALDH1A1, CXCR4, EpCAM, OCT-4, c-MYC, and NESTIN are cancer stemness-related markers of pancreatic cancer." (PMID 35806187, 2022). "In pancreatic cancer, the ablation of the oncogenic drivers mutant KRAS and c-MYC induces a dormant state, allowing the survival of a few residual cancer cells, which rely on autocrine IGF1/AKT as an adaptive mechanism." (PMID 35158815, 2022). "In pancreatic cancer, the ablation of the oncogenic drivers mutant KRAS and c-MYC induces a dormant state, allowing the survival of a few residual cancer cells that rely on autocrine IGF1/AKT as an adaptive mechanism." (PMID 35158815, 2022). "In pancreatic cancer, FTO mediated the m6A demethylation of the c-Myc transcript, resulting in increased c-MYC expression." (PMID 35350378, 2022). "Blockade of long-term ERK signaling also induces senescence through MYC degradation and p16 reactivation in KRAS-mutant pancreatic cancer." (PMID 35614034, 2022). "c-MYC acts as a cooperative downstream oncogenic factor to KRAS and has been shown to be overexpressed in both primary and metastatic pancreatic tumors." (PMID 34947972, 2021).